MALAT1 (metastasis associated lung adenocarcinoma transcript 1)
Diseases named in the same sentence as MALAT1 in open-access papers (continued):
Sharing a sentence is not in itself a finding about the gene and the disease.
cancer (continued). "More broadly, MALAT1 upregulation has been observed in many human cancers, which suggests that it is a ubiquitous metastatic driver." (PMID 33803619, 2021). "Analyzing the K562-MALAT1 and HeLa-MALAT1 models provides insights into the roles and mechanisms of MALAT1 in two different cancer cell lines: K562 and HeLa cells." (PMID 33450947, 2021). "In recent years, several circulating lncRNAs have been proved as suitable diagnostic and prognostic markers in various cancer types, such as prostate cancer antigen 3 (PCA3) and MALAT1." (PMID 34527584, 2021). "We also identified the immunological significance of MALAT1 in various kinds of cancers and demonstrated that MALAT1 was closely correlated with the infiltrating immune cell in various tumors." (PMID 34308750, 2021). "In BLCA, MALAT1 RNA level correlated with CD8 + T cell, CD4 + T cell, DC cell, Tregs cell, Mast cell, cancer-associated fibroblast, common lymphoid progenitor, eosinophil, MDSC, T cell NK, and T cell follicular helper cell infiltration." (PMID 34308750, 2021). "Online target prediction showed that two target sites for MALAT1 existed in miR-188-5p, which has been identified as a tumor suppressor in other types of cancers." (PMID 33944676, 2021). "First, MALAT1 expression levels in different clinical carcinoma tissues and cancer cell lines were investigated." (PMID 34638541, 2021). "Similar to miRNAs, compound 5 targets the 3′ element of the lncRNA metastasis-associated lung adenocarcinoma transcript 1 (MALAT1), providing a potential therapy for MALAT1-driven cancers." (PMID 34708037, 2021). "LncRNA MALAT1 exerted either oncogenetic or tumor‐suppressive roles in various cancers, including lung, breast, gastric, gallbladder, and colorectal cancers." (PMID 34240756, 2021). "MALAT1 can also affect pre-mRNA splicing by interacting with splicing factors, and in cancers, MALAT1 expression is upregulated by HIF-1αor hypoxia." (PMID 34044272, 2021). "For example, MALAT1 is a lncRNA that acts as a marker in various cancers, and miR-182-5p can reduce the proliferation of ccRCC by binding with MALAT1." (PMID 34616452, 2021). "One of the first identified lncRNAs is MALAT1, which promotes cancer proliferation and metastasis via gene expression and alternative splicing." (PMID 34044272, 2021). "MALAT1 as one of the earlier identified lncRNAs in cancer is investigated by more and more scientific researchers." (PMID 34308750, 2021). "Of note, the lncRNA MALAT1 exhibited the higher expression, similar to TG in differentiated cancer, with similar extent in both differentiated and undifferentiated thyroid cancer." (PMID 33030666, 2021). "In recent years, lncRNA MALAT1 has been proved to be a metastasis and prognosis marker of some cancers, and it was involved in the proliferation, invasion, and apoptosis of cancer cells." (PMID 34199840, 2021). "MALAT1 regulates cancer processes by interacting with molecules, such as proteins, RNAs and DNAs, and further alters different signal pathways." (PMID 35127729, 2021). "We first analyzed, by ddPCR expression of several cancer-associated lncRNAs (MALAT1, NEAT1, HOTAIR, H19, PVT1, MEG3) in both FNAs and surgical specimens and selected MALAT1, HOTAIR, and PVT1 as cancer biomarkers." (PMID 33030666, 2021). "One such lncRNA, metastasis-associated lung adenocarcinoma transcript 1 (MALAT1), is upregulated in many cancer types and has a myriad of protein- and miRNA-binding sites." (PMID 33450947, 2021). "For example, MALAT1 lncRNA, typically overexpressed in cancers, is m1A methylated in the A8398 position." (PMID 33430133, 2021). "Herein, we observed the consistent upregulation of MALAT1 in MYST4-overexpressing cell lines, while MALAT1 was frequently found to be upregulated in various types of clinical carcinoma tissues, especially EOC." (PMID 34638541, 2021). "Our investigation also revealed that MALAT1 was highly expressed among carcinoma tissues from various organs, including EOCs, as previously reported." (PMID 34638541, 2021).
cancer (continued). "MALAT1, a nuclear-restricted housekeeping regulatory lncRNA located on chromosome 11q13, was reported to be overexpressed across various human carcinoma types." (PMID 34638541, 2021). "Accumulating evidence indicates that lncRNA MALAT-1 is overexpressed in several types of solid cancers including lung, breast, gastric, bladder, and pancreatic cancers." (PMID 33052949, 2020). "Recently, MALAT1 was reported to bind EZH2 in many types of cancer, indicating the important regulatory relationship between these two elements." (PMID 32972446, 2020). "Key lncRNAs in angiogenesis such as MALAT-1 are deregulated in various cancer types, influencing angiogenesis by affecting different mechanisms." (PMID 32992718, 2020). "MALAT1, as mentioned in the introduction, is yet another lncRNA that has been studied intensely in recent years due to its involvement in cancer, for example by regulating alternative splicing." (PMID 32340118, 2020). "LncRNAs NEAT1 and NEAT2 also known as MALAT1 are among the best described non-coding RNAs in human diseases and were proposed as possible targets for anti-cancer therapies." (PMID 33213097, 2020). "Accumulating evidence suggested that lncRNA MALAT1 plays critical roles in the commencement and progression of malignant cancers." (PMID 33344634, 2020). "To confirm the suggested probable involvement of MALAT1 in the poor cellular differentiation status and disease progression, we first analyzed the expression level of MALAT1 in a public cancer database." (PMID 32326045, 2020). "An intriguing result was the observation of the downregulation of two long non-coding RNA, which are key players in many different types of cancers, MALAT1 and NEAT1." (PMID 33193626, 2020). "The metastasis-associated lung adenocarcinoma transcript 1 (MALAT1) is one of the earliest identified lncRNAs, and its role in cancer as a promoter of tumor progression and metastasis is well-defined." (PMID 33375130, 2020). "As an important lncRNA, MALAT1 has been described as a decisive gene in various cancers regulating metastasis." (PMID 31792655, 2020). "A recent study identified the secondary structure of MALAT1, an important cancer-related lncRNA, in vitro and in various human cell lines." (PMID 32429086, 2020). "Another study indicated that ANRIL, HOTAIR and MALAT1 were significantly down-regulated in cancer tissue compared to adjacent normal tissues." (PMID 32947877, 2020). "Another downstream target of MALAT1 is miR-429, which is considered as a potential biomarker for diagnosis of different cancers." (PMID 32664703, 2020). "For example, oncogenes like PCAT-1, MALAT1, and NDRG4 which associated with progression in pan-cancer had also been identified as prognostic biomarkers in CRC." (PMID 33203797, 2020). "It is compelling that this wide range of studies have identified MALAT1 as being strongly enriched in various body fluids of cancer patients and warrants MALAT1 to be further evaluated as a potential prognostic or diagnostic marker." (PMID 32503170, 2020). "In several genomic loci, NEAT1 colocalize with MALAT1 with independent but correlative activities, and it is involved in the regulation of different genes, including some genes controlling cancer progression." (PMID 33193626, 2020). "Collectively, these studies indicate a direct role for MALAT1 in hypoxic stress which is responsible for significant pathological consequences in cancer including angiogenesis and metastasis." (PMID 32503170, 2020). "Indel mutations in the MALAT1 and MIR122 host gene loci were identified in a pan-cancer analysis of somatic mutation hotspots." (PMID 33329688, 2020). "For example, MALAT1, an oncogene across numerous cancers, is restricted to the nucleus and plays a housekeeping role in splicing." (PMID 32024996, 2020). "For example, MALAT1 was found to be upregulated and to modulate the activity of cancer stem cells and radio-resistance by regulating the miR-1/slug axis in NPC." (PMID 32889799, 2020).
cancer (continued). "Intriguingly, we found two bromodomain containing proteins (BRD2 and BRD3) noted to be relevant in cancer interacting with MALAT1." (PMID 32050583, 2020). "Nevertheless, several studies demonstrated that MALAT1 augments the oncogenic activities of EZH2 in different types of cancer." (PMID 32760219, 2020). "To understand if MALAT1 can indeed effect cancer cell metastasis, we performed invasion assay using KRIB cells." (PMID 32728178, 2020). "Analysis of the eligible samples revealed that recurrent patients show high values for all the variables associated with the severity of cancer and exhibit high expression levels for ME3, PDK3, CHKA, and MALAT1 transcripts." (PMID 33375130, 2020). "We postulated that organs differ in the mechanism of MALAT1 involving the development and advance of cancer." (PMID 31792655, 2020). "Recent evidence of the roles of lncRNAs in cancer chemoresistance, such as the role of the lncRNA MALAT1 in cisplatin and that of linc00173 in adriamycin and etoposide resistance, has also added to our knowledge of cancer biology." (PMID 32727463, 2020). "MALAT1 is highly conserved in mammals, and previous studies have shown that played a critical role in the tumorigenesis of many cancers." (PMID 32720739, 2020). "As an lncRNA exerting oncogenic effects in many cancers, MALAT1 participates in a wide range of cellular processes." (PMID 32720739, 2020). "Recently, some meta-analyses have indicated that MALAT-1 has prognostic value in various human cancers as well as NSCLC." (PMID 33052949, 2020). "MALAT1, an evolutionarily conserved lncRNA that regulates mRNA splicing, is upregulated in several types of human cancers and is involved in cancer cell proliferation." (PMID 35006436, 2020). "Thirty-five cancer-relevant lncRNAs were identified, including the oncogenic lncRNAs MALAT1 and UCA1 and lncRNAs GAS5 and TUG1, which act as tumor suppressors." (PMID 33519750, 2020). "Higher levels of MALAT1 have also been observed in circulating RNAs, and also RNAs extracted from exosomes from cancer patients." (PMID 32503170, 2020). "In cancer, elevated levels of lncRNAS, like MALAT1, THOR, SAMMSON and SChLAP1 predict lower survival." (PMID 32742689, 2020). "For example, the lncRNA metastasis-associated lung adenocarcinoma transcript 1 (MALAT1), which regulates alternative splicing, is upregulated in many solid tumors including HCC, and is associated with cancer metastasis and recurrence." (PMID 32872482, 2020). "Metastasis associated lung adenocarcinoma transcript 1 (MALAT1) is a highly conserved long noncoding RNA, which has been related to various pathological processes, including cancer." (PMID 31733641, 2020). "All these data suggested that MALAT1 acted as a cancer‐promoting factor in the carcinogenesis of NSCLC." (PMID 33146951, 2020). "We wondered if genetic inactivation of MALAT1 can induce AMT in the well-characterized predominantly amoeboid cancer cell line A375m2." (PMID 32369931, 2020). "Together, these studies provide compelling evidence for targeting MALAT1 in multiple cancer types to achieve a therapeutic benefit." (PMID 32503170, 2020). "An example of a cancer-associated lncRNA that contains a SIRLOIN and is retained in the nucleus by hnRNPK is MALAT1." (PMID 32340118, 2020). "As a result, the hub-hub subnetwork was composed of all these hubs and their 103 edges, including the known cancer-related lncRNAs MALAT1 and XIST." (PMID 32802855, 2020). "Several lncRNAs such as HOTAIR or MALAT1 are known to exert an important influence in cancer, but there are many other lncRNAs whose role in cancer remains unexplored." (PMID 33333852, 2020). "In ceRNA network, we found that MALAT1 as a highly conserved lncRNA whose overexpression has been shown in various cancers, such as breast, prostate, colon, and liver, especially in early stage metastasizing patients." (PMID 32426332, 2020).
cancer (continued). "Among these key lncRNAs found in this study, MALAT1 has been demonstrated to be related to various malignant tumours." (PMID 32993558, 2020). "ZFAS1, as a novel star lncRNA candidate after HOTAIR and MALAT1, is abnormally expressed in various cancers; however, few ZFAS1-related studies on PAAD have been published." (PMID 32550827, 2020). "The upregulation of MALAT1 in a variety of cancers, which combines with its pleiotropic roles in gene regulation, has become the focus for therapeutic interventions of cancers." (PMID 33291485, 2020). "Previous studies have indicated that MALAT1 can induce EMT in cancer cells by acting as ceRNAs to sink miR-141, miR-3064-5p, miR-200b, and miR-144-3p." (PMID 33274006, 2020). "As to the prognostic value of lnc-MALAT1 in human diseases, it has been identified as a valuable biomarker for disease prognosis in several cancers, while limited clinical studies have been found in AIS." (PMID 33111743, 2020). "An additional study has demonstrated that cancer cell-specific chromatin-chromatin interactions are formed at the MALAT1 locus under hypoxic stress, thereby implicating a novel role of MALAT1 in regulating hypoxic response in cancer." (PMID 32503170, 2020). "More comprehensive studies are therefore required to verify the oncogenic or tumour‐suppressive role in MALAT1 in cancers." (PMID 32779318, 2020). "Based upon the significant body of pre-clinical data MALAT1 is poised to be targeted by antisense or small molecule drugs to impact cancer progression and other inflammatory and metabolic disease indications." (PMID 32503170, 2020). "In this way, MALAT1 influences proliferation, invasion and migration of cancer cells through regulation of multitudinous known downstream genes, including several metastasis-related genes (CCT4/CTHRC1/ROBO1/MIA2) and cell cycle control genes (p21/p27/B-MYB)." (PMID 31792655, 2020). "Metastasis-associated lung adenocarcinoma transcript 1 (MALAT1) is one of the most-studied lncRNAs, mostly associated with cancer and metastasis." (PMID 32180794, 2020). "After that discovery, the function of MALAT1 was studied in various cancers for its role in cancer development and progression." (PMID 33134293, 2020). "A variety of factors act as down-stream mediators for lncRNA MALAT1 and it appears that MALAT1 is capable of targeting miRs in cancer cells." (PMID 32664703, 2020). "An increasing number of studies have documented the clinical significance of MALAT1 in predicting cancer progression, and in playing diverse roles in regulating gene transcription, post-transcription, translation, and epigenetic modification." (PMID 32708561, 2020). "In a variety of cancer cell types, hypoxia induces expression of lncRNAs MALAT1, ZEB2-AS1 and HOTAIR, which are master regulators of alternative splicing, miRNA sponging, EMT, invasion, migration, cancer staminality and metastatic growth." (PMID 32536347, 2020). "Similar observations of upregulation of MALAT1 has been reported in drug resistance phenotypes in lung, prostate and other cancers." (PMID 32503170, 2020). "High expression of MALAT1 was relatedto large tumor size (>3 cm), poor histological grade, advanced cancer and tumor metastasis in NSCLC." (PMID 31863664, 2020). "Early studies consistently showed that MALAT1 is highly expressed in cancerous tissue and facilitates tumour progression and metastasis in various cancers." (PMID 32779318, 2020). "Taken together, MALAT1 appears important not only in cancer development but also in the progression of IS, but the exact mechanism is still not fully elucidated." (PMID 32238151, 2020). "MALAT1, one of the most studied lncRNAs due to its role in various cancer types, was shown to promote VM in lung and gastric cancer." (PMID 33333852, 2020). "Apart from chromosomal aberrations in the MALAT1 locus in cancer, WGS studies from patient tumors have found that MALAT1 is a frequently mutated gene in breast and other cancer types." (PMID 32503170, 2020).